WT1 (WT1 transcription factor)
Diseases named in the same sentence as WT1 in open-access papers (continued):
Sharing a sentence is not in itself a finding about the gene and the disease.
tumor (continued). "Whether loss of NEK1 might coexist with β-catenin stabilization, similarly to WT1 alterations, for the survival and proliferation of tumor cells is an open question." (PMID 26317783, 2015). "Significantly higher WT1 mRNA levels were detected in tumor specimens compared to adjacent tumor-free tissue samples (p < 0.001) and normal control tongue tissues (p=0.001), indicating overexpression of WT1 in SCCHN." (PMID 25929687, 2015). "The WT1-wild-type tumours show a closer phenotypic resemblance to the effects of the post-MET Pax8+/Cre-mediated loss of Wt1, even though the initiating genetic event will be different for these tumours." (PMID 26035382, 2015). "Indeed, with the present therapies, the WT1-mutant subset of tumours is much better treatable than their WT1-wild-type counterpart." (PMID 26035382, 2015). "Although the initiating event would be different (and currently unknown) from the WT1-mutant subset, the developmental stage at which this initiating event would occur would be the same as in WT1-mutant tumours." (PMID 26035382, 2015). "In contrast, in sporadic, non-syndromic WT, tumor predisposition is usually not the result of WT1 constitutive mutations." (PMID 26317783, 2015). "WT1 expression was associated with high FNCLCC grade and advanced tumor stage (P = 0.000)." (PMID 25026998, 2014). "Increased expression of WT1 has been previously reported in ccRCC patient tumor samples." (PMID 25025131, 2014). "The cell type, its current state of development and the ratio of WT1 isoform expression may be crucial for WT1 to either promote or suppress tumor development." (PMID 24955840, 2014). "An immunohistochemical analysis of the tumor samples indicated positivity for WT1 and MUC1." (PMID 25526950, 2014). "The Wilms' tumor gene (WT1) was among the first tumor suppressor genes to be cloned." (PMID 25375204, 2014). "To complement these experiments, we investigated whether exogenous WT1 would affect tumor growth in SK-ES-1 cells." (PMID 24810959, 2014). "Moreover, WT1 silencing reduced in vivo the number and growth of visible metastatic tumor foci in the lungs through aerosol delivery of PEI-WT1 RNAi complexes." (PMID 25474318, 2014). "However, clinical immunotherapeutic use of WT1 antigenic peptides against different types of neoplasms remains inconclusive." (PMID 28548069, 2014). "Tumor growth was substantially diminished by knockdown of WT1 expression." (PMID 24810959, 2014). "Thus, our results demonstrate that WT1 expression directly regulates tumor angiogenesis by controlling the expression of a panel of pro-angiogenic genes." (PMID 24810959, 2014). "We suggest that WT1-induced EMHT is involved in providing phenotypic plasticity to tumor cells." (PMID 25025131, 2014). "Furthermore, SmartDCtWT1 immunization plus adoptive transfer of T cells reactive against WT1 into mice resulted in growth arrest of a WT1+ tumor." (PMID 28548069, 2014). "Second, the expression of MHC class I molecules may be lower in physiologically WT1 expressing normal cells than in WT1 expressing tumor cells." (PMID 25026998, 2014). "Results were consistent with the prior analysis by microarray, demonstrating roughly 2–4 fold hypermethylation across all eight CpG sites analyzed in the WT1 imprinting control region (including cg22533573 ) in comparing individual tumor and adjacent normal tissue pairs." (PMID 23890537, 2013). "Immunohistochemically, the tumor cells of the metanephric tumor are positive for WT-1 and CD57." (PMID 24083046, 2013). "Peripheral blood mononuclear cells obtained by leukapheresis were cultured with granulocyte-macrophage colony-stimulating factor, interleukin-4, OK-432 and prostaglandin E2 to generate DCs, which were pulsed with autologous tumor lysates or tumor-specific peptides, such as WT1." (PMID 24649223, 2013). "More analyses will be needed to determine if the WT1-mutant tumours also harbour NCAM+ALDH1+ CSC." (PMID 23239670, 2013).
tumor (continued). "As a tumor suppressor gene, WT1 was previously shown to repress PMA induced transcription." (PMID 23874238, 2013). "Furthermore, the genetic aberrations that drive the WT1-wild type tumours need to be clarified before their influence on the NCAM+ALDH1+ CSC can be taken into account." (PMID 23239670, 2013). "We demonstrate that Wt1 ablation and Igf2 upregulation in tumors results in up-regulation of glucose utilization during initial stages of tumor development, followed by a gradual decrease in tumor glycolytic activity, consistent with the development of large areas of hemorrhagic necrosis." (PMID 22875335, 2013). "We performed immunostaining of p-WT Xn and parental WT for the following: WT1, a specific clinical diagnostic marker for WT; NCAM1, a putative marker for a tumour progenitor population previously shown in in vitro assays of primary cell cultures of WT; and Ki-67, a cell proliferation marker." (PMID 23239665, 2013). "Furthermore, SRPK1, the protein kinase that promotes the entry of SRSF1 into the nucleus, is transcriptionally repressed by the Wilms tumour suppressor WT1." (PMID 24101931, 2013). "Sequence analysis was performed on all 10 exons in WT1 in 182 ccRCC tumour specimens." (PMID 23484026, 2013). "The Zinc finger protein WT1 was initially identified as a tumor suppressor gene in Wilms’ tumors." (PMID 24228711, 2013). "Immunohistochemical staining of the BIN-67-derived tumours revealed a diagnostic expression pattern that is similar to that reported in humans, notably intense expression of WT-1 and vimentin and lack of expression of inhibin." (PMID 23433318, 2013). "However, the ability of WT1 to induce growth suppression and suppress tumorigenicity in mice also highlights its role as a tumor suppressor." (PMID 22244202, 2012). "Furthermore, in this study, we also show that IL-15 DCs, as would be expected from DCs, are capable of processing and presenting the WT1 tumor antigen to CD8+ T cells." (PMID 23284789, 2012). "Depending on the cell type, WT1 had either tumor-promoting or tumor-suppressing function." (PMID 22133358, 2011). "It has been proposed that WT1 might be an oncogene in adult cancer in contrast toits function as a tumour suppressor in paediatric kidney cancer." (PMID 22216009, 2011). "Thus, ablation of HtrA2 in two different tumor cell lines by siRNA blocks the induction of WT1 cleavage by cytotoxic drugs." (PMID 20122399, 2010). "WT1 cofactors that block HtrA2-mediated processing of WT1 could potentially provide a switch that regulates the dichotomy of the tumor suppressor and oncogenic properties of WT1." (PMID 20122399, 2010). "In addition to nuclear WT1 protein, we and others have observed WT1 protein in the cytoplasm of several tumor types, and this is consistent with the presence of a cytoplasmic localization signal on the WT1 protein." (PMID 20426842, 2010). "Nonevaluable primary tumors due to core loss during staining procedures or absence of tumor tissue ranged from 19 (7.4%) for SP17 staining to 41 (15.2%) for WT1 staining." (PMID 20885926, 2010). "Both cytoplasmic and nuclear WT1 staining has been shown in other tumor types." (PMID 20426842, 2010). "Wilms' tumour 1 (WT1) gene was discovered as a tumour suppressor gene." (PMID 20842112, 2010). "Furthermore, Pea3 activates transcription of multiple neoplasia-associated genes, including MMP genes, COX-2, Twist, osteopontin, uPA, vimentin, MUC4, WT1, mammaglobin, cyclin D3 and HER2." (PMID 20107508, 2010). "However, further studies, especially on mechanisms of immune evasion at the effector phase of the anti-tumor immune response, are indicated to determine potential inhibitory immune mechanisms during WT1 peptide vaccination." (PMID 20092642, 2010). "Human cytotoxic T lymphocytes (CTLs), which could specifically lyse WT1-expressing tumor cells with HLA class I restriction, were generated in vitro." (PMID 17619750, 2007).
tumor (continued). "Two tumours (#9 and #10) expressed a certain level of WT1 in spite of a homozygous deletion, which might be due to contamination with nontumour cells." (PMID 16909133, 2006). "Excluding tumours with homozygous deletions, six tumours (17%) had a reduction in WT1 expression." (PMID 16909133, 2006). "Only one tumour had concurrent homozygous deletion of the WT1 gene." (PMID 16909133, 2006). "As SF-1 and WT1 are involved in the development of tumour, the FATE/BJ-HCC-2 may also be involved in tumourigenesis." (PMID 12865919, 2003). "Overall, the absence of additional driver variants in tumours arising on a background of WT1 or TRIM28 predisposition was significant, even when solely considering high risk variants, whether compared to other predispositions or to control tumours (p<0.05, Fisher’s exact test)." (PMID 39665570, 2025). "Especially WT1-driven tumors follow a stereotypical pathway of germline WT1 mutations becoming homozygous in renal precursor lesions through 11p LOH, which concomitantly activates imprinted IGF2 expression, with subsequent WNT pathway activation leading to tumor growth." (PMID 40340749, 2025). "WT1 is frequently overexpressed in HNSCC and has an impact on cell proliferation through multiple genes involved in cell proliferation, cell cycle regulation, and DNA replication, and is closely associated with poor tumor differentiation and high tumor stage in HNSCC histology." (PMID 40491907, 2025). "However, in the differential gene expression analysis, the anti-WT1 T-cells exhibited higher expression of ZNF683 and S1PR, both of which have been associated with effective antitumor responses and persistence in tumor-infiltrating lymphocytes." (PMID 40847198, 2025). "However, the identification of myoepithelial markers (such as WT1 and P63) may help confirm the tumor’s cutaneous origin." (PMID 40969274, 2025). "Moreover, the WT1 protein level was detected using immunofluorescence in the tumor tissue." (PMID 38742454, 2024). "Therefore, this study aimed to investigate whether WT1-specific CTLs are clonally expanded in the PB outside the tumor site of patients to comprehensively understand the nature of the anti-cancer immune response in patients with solid cancer." (PMID 39509060, 2024). "Therefore, a large amount of WT1 antigen was likely released from collapsed WT1-expressing tumor cells during these treatments, which endogenously induced WT1-specific CTLs, followed by clonal expansion in association with cell proliferation and differentiation from naïve to memory phenotypes." (PMID 39509060, 2024). "Therefore, we investigated whether WT1-specific cytotoxic CD8+ T-lymphocytes (CTLs) are clonally expanded in the peripheral blood outside of tumor sites." (PMID 39509060, 2024). "The presence of clonally expanded WT1126-specific CTLs with advanced differentiation stages in the PB of solid tumor patients prior to WT1 peptide vaccine therapy suggests that these CTLs may rapidly trigger tumor attack after WT1 peptide vaccine administration." (PMID 39509060, 2024). "In addition to the common EWSR1::WT1 fusion, DSRCTs commonly display alterations in other pathways that make the tumor more aggressive and allow it to spread early in its development, prompting tumor metastasis." (PMID 39682287, 2024). "All WT1-expressing tumor cells could be targets of WT1-specific CTLs." (PMID 36672344, 2023). "Therefore, future knowledge of germline WT1 status at diagnosis in patients with BWT could guide expectations regarding volumetric tumor regression and timing of surgical resection." (PMID 38110397, 2023). "The extended length between the two arms, exceeding 140 Å, may result in less efficient formation and reduced duration of the immunological synapses between T cells and tumor cells, especially given the low number of WT1-HLA-A*02:01 pMHCs on tumor cell surface." (PMID 38022650, 2023).
tumor (continued). "Therefore, it can be inferred that the germline genetic WT1 variants that lead to BWT predisposition occur on the paternal allele and become homozygous in the tumor due to copy neutral LOH events at 11p13-11p15.5 loci that establish paternal uniparental disomy." (PMID 38110397, 2023). "In addition, FCER2, CD200R1, and RHOV in the signature were strongly associated with the clinical stage of the tumor, and univariate cox analysis showed that except for TNNT2, WT1 and KRTAP5-8, the remaining signature genes were closely correlated with the prognosis of LUAD patients." (PMID 37234773, 2023). "Therefore, although the Wt1 gene was originally described as a classic tumor suppressor gene, the Wt1 gene may act as a proto-oncogene in many cases." (PMID 36829196, 2023). "Recently, in a ranking of 75 tumor antigens based on characteristics such as therapeutic function, immunogenicity, oncogenicity, and specificity, MUC1 received the second-best rating (after WT1), underlining its potential for medical research and vaccine development." (PMID 37894512, 2023). "No mutations in the WT1 gene were identified in the constitutional and tumor DNA of the twins." (PMID 35205416, 2022). "Since WT1 and IL-24 are rarely expressed in KIRC tissues, we investigated the clinical prognostic significance of WT1-regulated genes, including GDD45A and TXNIP, finding that the levels of these genes were associated with the histological grade, tumor stage, and metastasis in KIRC patients." (PMID 35915803, 2022). "Thus, it seems that WT1 may not only facilitate tumor dissemination, but also cancer resilience, increasing tumor cell survival through its anti-apoptotic function." (PMID 35453662, 2022). "Therefore, whether WT1 acts as an inhibitor or promoter of tumor cell proliferation varies with different tumor tissues and is tissue-specific." (PMID 35915803, 2022). "Thus, whether WT1 acts as an oncogene or tumor suppressor in tumor cells depends on the regulatory network of genes in different cells, which may be an important reason why WT1 is known as the chameleon gene." (PMID 35915803, 2022). "In addition, WT1 inhibition significantly suppressed tumor growth of BRAFV600E PTC cells in vivo." (PMID 35123502, 2022). "Additionally, our data suggest that direct therapeutic targeting of the miR-642a-5p cell cycle target genes, in particular WT1, could produce significant anti-tumor effects to benefit PCa patients." (PMID 34504167, 2021). "Finally, we conclude that changes in WT1 isoforms during estrogen depletion in MCF-7 cells may play a role in hormone-independent adaptation to tumor growth." (PMID 34845427, 2021). "Investigating the long-term effects of WT1 peptide immunization with the Wc vaccine, the authors concluded the Wc vaccine doesn’t induce auto-immune responses and that repeated administration of the Wc vaccine together with a tumor peptide is therefore considered to be relatively safe." (PMID 34055652, 2021). "In this study, we found that the histidine in WT1 was a conserved residue and that the mutant variant could not function well as a tumor suppression gene." (PMID 33942367, 2021). "Additionally, a high expression of WT1 (Wilms tumor gene) mRNA in the aqueous humor was discovered." (PMID 31977890, 2020). "In both cases the WT1 mutation was tumor specific, i.e., not present in the germ line." (PMID 33379206, 2020). "However, the ascites-derived cell line OV3291 did not express WT1, despite its associated tumor of origin and corresponding tumor cell line TOV3921G expressing this protein." (PMID 32784519, 2020). "However, more studies are needed to discard the possibility that Wt1-5 could infect non-tumor cells." (PMID 32722005, 2020).
tumor (continued). "Indeed, numerous studies have indicated that alternative splicing occurs frequently in cancer cells, and a plethora of cancer-specific splice variants have been reported; and some of them are considered to be candidate cancer biomarkers, such as CD44 and the Wilms tumor (WT1) genes." (PMID 31440421, 2019). "Moreover, different isoforms of WT1 can determine whether it has a role as an oncogene or a tumor suppressor." (PMID 31561534, 2019). "Normal WT1 expression is essential for blastemal cells differentiation into the mature epithelial component of kidney parenchyma, and disruption of this expression may result in the development of cells with the potential for tumor formation." (PMID 30648000, 2019). "Concomitantly, many other haematological and solid tumours could benefit from WT1-directed therapy." (PMID 30678059, 2019). "Importantly, WT1332-specific CD4+ T cells could not only aid the expansion of WT1-specific CD8+ CTLs but also directly kill HLA class II-positive WT1-expressing tumor cells." (PMID 30430205, 2019). "Moreover, the transcription factor Wt1 accumulates in the cytoplasm of malignant cells leading to the hypothesis that a disparate subcellular localization of Wt1 in normal and cancer cells contributes to its dual functions as tumor suppressor and oncogene." (PMID 30469340, 2018). "Moreover, we intentionally avoided the use of WT1-inducible system and we preferred an already established WT1-positive tumor cell line because the applicable over-expressing system may reflect the function of WT1 only to a limited extent." (PMID 28107196, 2017). "By targeted sequencing of WT1 in eight bilateral WTs (defined in this case as only synchronous bilateral tumours), three patients were found to have germline heterozygous nonsense mutations in WT1 exon 8, leading to WT1 protein truncation with no wild-type allele present in the tumours (Ref." (PMID 28716159, 2017). "Therefore, UB-equivalent structures are also present in all WT1-mutant tumours." (PMID 29040332, 2017). "Using DHPLC and DNA sequencing, no pathogenic mutation of WT1 was found in blood or tumor DNA." (PMID 27213811, 2016). "Notably, whereas all samples show enrichment for some cell-division-related GO terms, the WT1 wild-type tumours show enrichment for regulation of every possible aspect of cell cycle control, including every phase transition, spindle functions, checkpoints, DNA replication and chromosome separation." (PMID 26035382, 2015). "Similarly, WT1 mediates BCR-ABL induced repression of the myeloid tumor suppressor IRF8." (PMID 26320177, 2015). "The effects of inhibition of SRPK1 and SRPK2 by the compounds may be revealed using in vivo tumor models with WT1 mutations rather than cell culture models." (PMID 25581376, 2015). "First, it may be due to normal cells having lower WT1 expression than tumor cells." (PMID 25026998, 2014). "In this work we tested the hypothesis that WT1 expression regulates tumor angiogenesis." (PMID 24810959, 2014). "Therefore, WT1 overexpression could potentially be used as a tumor-specific target for cancer treatment." (PMID 24667279, 2014). "Previous studies have suggested that WT1 may play an oncogenic role in this type of tumour." (PMID 23484026, 2013). "In addition, we have assayed two other tumour-suppressor genes, WT1 and NF1, to see whether they play a role in colorectal carcinogenesis." (PMID 7947085, 1994). "For instance, the immunoprofiles of most testicular SCSTs show substantial overlap, with purported ‘sex cord markers’ such as WT1, FOXL2 and SOX9 being expressed in tumours with seemingly pure stromal phenotype and vice‐versa." (PMID 41384702, 2026).